CAPZA2 (capping actin protein of muscle Z-line subunit alpha 2)
Description:
F-actin-capping proteins bind in a Ca(2+)-independent manner to the fast growing ends of actin filaments (barbed end) thereby blocking the exchange of subunits at these ends. Unlike other capping proteins (such as gelsolin and severin), these proteins do not sever actin filaments.
Synonyms: CAPZ; CAPPA2
Tractability: Antibody: its Gene Ontology location is reachable by antibodies, with high confidence. PROTAC: ubiquitination databases record sites on it; its protein half-life has been measured.
Gene: Protein-coding gene on chromosome 7 (116,811,070 to 116,922,049, forward strand). Ensembl gene ENSG00000198898.
Subcellular location (Human Protein Atlas): Cytosol
Pathways (Reactome):
Immune System: Advanced glycosylation endproduct receptor signaling; MHC class II antigen presentation
Vesicle-mediated transport: COPI-independent Golgi-to-ER retrograde traffic; COPI-mediated anterograde transport
Cellular responses to stimuli: HSP90 chaperone cycle for steroid hormone receptors (SHR) in the presence of ligand
Hemostasis: Factors involved in megakaryocyte development and platelet production
Sensory Perception: Sensory processing of sound by inner hair cells of the cochlea
Gene Ontology:
Molecular function: protein binding; actin filament binding
Biological process: barbed-end actin filament capping; protein-containing complex assembly
Cellular component: extracellular exosome; actin cytoskeleton; cortical cytoskeleton; cytosol; extracellular region; F-actin capping protein complex; brush border; membrane
Genetic constraint (gnomAD): Loss-of-function variants: 2 observed, 14.18 expected, observed/expected ratio (o/e) 0.14, 90% interval 0.057 to 0.44. The upper end of that interval is the gene's LOEUF score, 0.44, which puts it in group 1 of 6, group 1 being the genes least tolerant of losing a copy. Missense variants: 86 observed, 124.07 expected, observed/expected ratio (o/e) 0.69, 90% interval 0.58 to 0.83. Synonymous variants: 41 observed, 42.14 expected, observed/expected ratio (o/e) 0.97, 90% interval 0.76 to 1.26.
Homologues: Orthologues: chimpanzee CAPZA2 (100% identical), dog CAPZA2 (99% identical), pig CAPZA2 (99% identical), mouse Capza2 (98% identical), rat Capza2 (98% identical), guinea pig CAPZA2 (96% identical), macaque CAPZA2 (96% identical), tropical clawed frog capza2 (87% identical), Drosophila melanogaster cpa (60% identical), Caenorhabditis elegans cap-1 (52% identical). Paralogues in human: CAPZA1 (87% identical), CAPZA3 (36% identical).
Diseases named in the same sentence as CAPZA2 in open-access papers:
CAPZA2 is named in the same sentence as 24 diseases in open-access papers, as found by Europe PMC text mining. Sharing a sentence is not in itself a finding about the gene and the disease. The quoted sentences say what the papers report.
glioblastoma (5 papers, 2013 to 2022). The most malignant astrocytic tumor (WHO grade IV). "Four of these seven cases relate to glioblastoma in which fusion pairs CAPZA2-MET and FIP1L1-PDGFRA, CAPZA2-MET and MET-MET, EGFR VIII and PTPRZ1-MET, PTPRZ1-MET and TBL1XR1-PIK3CA were identified." (PMID 35984852, 2022). "Research has shown that CAPZA2 was amplified in more than 20% of glioblastomas." (PMID 23545944, 2013). "AP1B1, adaptor related protein complex 1 beta 1 subunit; CAPZA2, F-actin-capping protein subunit alpha-2; CCT5, chaperonin containing TCP1 subunit 5; GBAS, glioblastoma amplified sequence; RPS21, 40 S ribosomal protein S21." (PMID 30931934, 2019). "Identified were five fasting-responsive proteins that overlapped between the lines, including adaptor related protein complex 1 beta 1 subunit (AP1B1), CAPZA2, chaperonin containing TCP1 subunit 5 (CCT5), glioblastoma amplified sequence (GBAS), and 40 S ribosomal protein S21 (RPS21)." (PMID 30931934, 2019). "Interestingly, a broad range of actionable fusion genes were identified in this cohort of glioblastomas including EGFR-SEPT, EFGR intragenic recombination, FGFR3-TACC3, PTPRZ1-MET, CAPZA2-MET, METex14 skipping, AGK-BRAF, EGFR Viii, TBLXR1-PIK3CA and FIP1L1-PDGFRA." (PMID 35324914, 2022).
gastric cancer (3 papers, 2017 to 2022). A primary or metastatic malignant neoplasm involving the stomach. "CAPZB has oncogenic potential, CAPZA1 inhibits cancer cell migration in gastric carcinoma while CAPZA2 promotes gastric cancer cell migration and invasion." (PMID 36291816, 2022). "No recurrent MET fusions were identified, some of the fusion partners included HLA-DRB1-MET (lung cancer), CD47 (lung cancer), CAPZA2 (gastric cancer), AKAP9 (hepatobiliary cancer), CLIP2 (hepatobiliary cancer), and SLC25A19 (ovarian cancer)." (PMID 36369474, 2022). "A high frequency of CAPZA2 amplification was found in ovarian cancer, esophageal cancer, melanoma, and lung adenocarcinoma, as well as stomach cancer." (PMID 29190909, 2017).
Intellectual disability (2 papers, 2022 to 2025). "Mutations in CAPZA2 can cause intellectual disability and developmental delay." (PMID 40898360, 2025). "However, a skeletal muscle function has only been discovered for CAPZA2, as patients carrying CAPZA2 variants suffer from hypotonia as well as intellectual disability, speech delay, and seizures." (PMID 35148320, 2022).
adrenogenital disorder (1 paper, 2025). "On the other hand, we observed two significantly upregulated proteins in the urine proteome of patients with adrenogenital disorder: haptoglobin (HP) and F-actin capping protein subunit alpha-2 (CAPZA2)." (PMID 40425748, 2025). "CAPZA2, which regulates actin filament dynamics, has not been previously associated with adrenogenital disorder." (PMID 40425748, 2025).
Alzheimer disease (1 paper, 2025). A progressive, neurodegenerative disease characterized by loss of function and death of nerve cells in several areas of the brain leading to loss of cognitive function such as memory and language. "While the role of CAPZA2 in neurodegeneration is not well understood, it has been shown to be down-regulated in CSF of patients with Alzheimer’s disease." (PMID 40898360, 2025).
anemia (1 paper, 2022). A reduction in the number of red blood cells, the amount of hemoglobin, and/or the volume of packed red blood cells. "In contrast to Samd14, which increases upon PHZ-induced anemia, Capzb and Capza2 mRNA and protein decreased after PHZ treatment in a population containing erythroid precursors (defined by surface markers CD71+Kit+Ter119-)." (PMID 35713400, 2022).
asthma (1 paper, 2023). "Specifically, we sought to examine causal mediation between PBMC key drivers associated with asthma (PRF1 and NKG7 in the NK cell module; CAPZA2, ATP6AP2, CTSS, and RAB3D from the interleukin module) and nasal key drivers associated with asthma (G3BP1 and INADL from the nasal TCA module)." (PMID 37730635, 2023).
breast carcinoma (1 paper, 2022). "A decrease in the transcription levels of human invasion signature (HIS) genes (ARHGDIB, CAPZA2, PHACTR2, CDC42, XRCC5, and CAV1) has been also demonstrated by real-time PCR, with high expression of these genes being a hallmark of actively metastasizing breast cancer cells." (PMID 36143471, 2022). "We have shown that OCT-1 knockdown suppresses the expression of the ARHGDIB, CAPZA2, PHACTR2, CDC42, XRCC5, and CAV1 genes, which is known to be increased in actively metastasizing breast cancer cells." (PMID 36143471, 2022).
cholangiocarcinoma (1 paper, 2024). A carcinoma that arises from the intrahepatic biliary tree (intrahepatic cholangiocarcinoma) or from the junction, or adjacent to the junction, of the right and left hepatic ducts (hilar cholangiocarcinoma). "A recent study reported a patient with cholangiocarcinoma harboring a CAPZA2–MET fusion along with MET amplification, who dramatically responded to capmatinib, a specific MET TK inhibitor." (PMID 38363490, 2024).
endometrial cancer (1 paper, 2015). Primary or metastatic malignant neoplasm involving the endometrium (mucous membrane that lines the endometrial cavity). "To assess the frequency of occurrence of the three in-frame kinase fusions (CPQ-PRKDC, VGLL4-PRKG1, CAPZA2-MET) in clinical samples, we conducted RT-PCR and Sanger sequencing for 122 primary endometrial cancer tissues." (PMID 26689674, 2015).
glaucoma (1 paper, 2023). Increased pressure in the eyeball due to obstruction of the outflow of aqueous humor. "ROC curves suggested that miR-106-5p-CAPZA2/CREB1 axis and miR-15a-5p-SLC2A3 axis (AUC > 0.9) exhibited excellent ability to distinguish POAG from non-glaucoma individuals." (PMID 37940950, 2023).
nemaline myopathy (1 paper, 2022). Nemaline myopathy (NM) encompasses a large spectrum of myopathies characterized by hypotonia, weakness and depressed or absent deep tendon reflexes, with pathologic evidence of nemaline bodies (rods) on muscle biopsy. "In addition, the aggregates of capza1b-deficient mutants featured characteristics of nemaline bodies indicating that individuals with CAPZA2 variants might suffer from nemaline myopathy." (PMID 35148320, 2022).
prostate carcinoma (1 paper, 2020). A carcinoma that arises from epithelial cells of the prostate gland. "Based on mRNA expression levels, the CAPZA1/B2 heterodimer is more prominently expressed than the CAPZA2/B2 in the PC-3 prostate cancer cells, which were used in most of our cellular assays." (PMID 32771000, 2020). "To obtain information on CP localization in PC-3 prostate cancer cells, we analysed the subcellular distribution of endogenously expressed CAPZA1, CAPZA2 and CAPZB2 from fractionated cells by Western blotting." (PMID 32771000, 2020). "Here we show positive correlations between PIM1 and either CAPZA1, CAPZA2 or CAPZB mRNAs in prostate cancer samples with different Gleason grades, but not in the healthy control tissues." (PMID 32771000, 2020). "On the other hand, phosphorylation of CAPZA2 was not studied in more detail and it may therefore play an as of yet unknown role in the regulation of e.g. nuclear actin dynamics in prostate cancer cells." (PMID 32771000, 2020).
cancer (6 papers, 2017 to 2023). A tumor composed of atypical neoplastic, often pleomorphic cells that invade other tissues. "However, the investigations about the role of CAPZA2 in cancer are rare." (PMID 31815141, 2019). "Fusion pairs were also identified in colon (CAPZA2-MET and MET-MET), lung (PIK3CA-TBL1XR1 and RET-NCOA4) and pancreatic (FNDC3B-PIK3CA and TBL1XR1-PIK3CA) cancers." (PMID 35984852, 2022).
tumor (3 papers, 2015 to 2020). "It is possible that CAPZA2 may play a role in tumor-specified cell motility." (PMID 31815141, 2019). "While CAPZA1, CAPZA2 and CAPZB, but not CAPZA3 levels correlated well with PIM1 levels in all tumor tissues, similar correlations were also observed for PIM2 and PIM3 in the samples with high Gleason scores." (PMID 32771000, 2020).
CAPZA2 also shares sentences with these, for which no sentence is quoted: ovarian carcinoma (2 papers); developmental delay (1); esophageal cancer (1); gastric adenocarcinoma (1); glioma (1); lung adenocarcinoma (1); lung carcinoma (1); melanoma (1); stomach cancer (1).